SETD2 (SET domain containing 2, histone lysine methyltransferase)
Diseases named in the same sentence as SETD2 in open-access papers (continued):
Sharing a sentence is not in itself a finding about the gene and the disease.
chordoma (7 papers, 2017 to 2025). Chordomas are rare malignant tumors arising from embryonic remnants of the notochord in axial skeleton. "Mutations in PBRM1, ARID1A, and SETD2 appear to be enriched in chordoma." (PMID 39941902, 2025). "It appears that a subset (20.3%) of chordoma is enriched with at least one SWI/SNF complex mutation: PBRM1, ARID1A, or SETD2." (PMID 39941902, 2025). "In SETD2, the T2338Hfs*31 mutation appears recurrently in exon regions (n = 2), which may indicate mutation hotspots within specific functional domains of the protein, potentially impacting chromatin modification functions critical to cancer biology in chordoma." (PMID 39941902, 2025). "Together with SETD2 alterations in three patients, alterations in these two chromatin remodeling genes accounted for 16% (13 of 80) of the chordoma tumors we sequenced." (PMID 33536423, 2021). "Mutations in three other SWI/SNF members—PBRM1, SETD2, ARID1A—have been identified as potential drivers in chordomas; however, the relevance of these mutations to chordoma etiology remains to be elucidated." (PMID 32733369, 2020). "Drivers in another SWI/SNF gene, PBRM1 (10/104 cases) and the histone methyltransferase, SETD2 (5/104) implicate defective chromatin modelling as a major driver of chordoma." (PMID 29026114, 2017). "Our findings of enrichments in SWI/SNF complex mutations, such as PBRM1, ARID1A, SETD2, and SMARCA2, indicate that epigenetic therapies may be effective in some chordoma cases." (PMID 39941902, 2025). "Interestingly, chordoma mutations in the PBRM1, ARID1A, or SETD2 genes are frequently missense mutations." (PMID 39941902, 2025). "Additionally, mutations within the chromatin remodeling genes PBRM1, SETD2, and SMARCB1, which have previously been recognized as frequently altered in chordoma, were each identified in two patients." (PMID 39135136, 2024). "Given the role of PBRM1 and SETD2 in chromatin remodeling, our data suggest that epigenetic dysregulation may play an important role in chordoma development." (PMID 33536423, 2021). "Chordomas commonly activate pathways such as EGFR, PDGFβ, IGFR1, IGF1, mTOR, MET, and PI3K and involve chromatin remodeling genes such as ARID1A, PBRM1, and SETD2." (PMID 39193055, 2024). "In summary, we identified candidate driver events (PBRM1+, SETD2+, CDKN2A/B+, TBXT/LYST+) in 33.75% (27 out of 80) of the skull-base chordoma patients we sequenced." (PMID 33536423, 2021). "In this cohort, composed of 116 patients with chordoma NOS, 14 with conventional chordoma, and 3 with dedifferentiated chordoma, mutations in SWI/SNF complex genes (PBRM1, ARID1A, SETD2) were not significantly enriched or depleted across subtypes (p > 0.05)." (PMID 39941902, 2025). "SNP-array combined with NGS analysis demonstrated nonrandom copy number losses across the genome of sacral chordoma patients, frequently involving 3, 9p, 1p, 14, 10, and 13, and two minimum deleted regions which covered SETD2 mapped on chromosome 3p." (PMID 34715919, 2021). "Notably, recurrent mutations in SETD2 (e.g., T2338Hfs31 in exon regions, n = 2) and PBRM1 (e.g., D1055Y, n = 2; W1417, n = 2) were absent from the COSMIC database’s chordoma entries, indicating potential novel hotspots." (PMID 39941902, 2025).
Intellectual disability (7 papers, 2020 to 2025). "For instance, SETD2-related disorders often exhibit intellectual disabilities, developmental delays, and heightened susceptibility to cancer as a result of impaired DNA repair and transcriptional regulation." (PMID 40469903, 2025). "All individuals with SETD2 LoF variants displayed macrocephaly and mild to moderate intellectual disability." (PMID 37166351, 2023). "Three patients who carried the missense variant p.Arg1740Gln in SETD2 were reported with a moderately impaired intellectual disability, speech difficulties, and behavioral abnormalities." (PMID 37372360, 2023). "Mutations in SETD2 have been linked to brain disorders such as intellectual disabilities and autism spectrum disorders." (PMID 34226540, 2021). "The dysregulation of SETD2 and H3K36 methylation has profound implications for neurodevelopment, contributing to neurodegenerative diseases, intellectual disabilities, and other related disorders." (PMID 40469903, 2025).
kidney tumors (7 papers, 2016 to 2025). "Our disease ontology analyses also showed that SETD2-dependent DNA methylation alterations were associated with altered expression of genes involved in kidney neoplasm and neoplasm invasiveness." (PMID 37528416, 2023). "Loss of SETD2 function is known to impact in kidney neoplasm formation through replication stress and impaired DNA repair." (PMID 37528416, 2023). "It has been reported that SETD2 mutations were more frequently found in the hypoxic group of kidney tumors, and the hypoxic group of HCC also had more patients with mutant SETD2 in our study." (PMID 36059442, 2022). "Intriguingly, human kidney tumours with SETD2 mutations are characterised by increased intron retention and altered transcription termination site usage." (PMID 32621610, 2020). "We have previously identified an evolutionarily conserved synthetic lethality between loss of SETD2 and WEE1 inactivation, and that renal tumours with loss of SETD2 or H3K36me3 can be specifically targeted with WEE1 inhibition, an observation that has been taken into clinical trials." (PMID 37528416, 2023). "Genes whose expression was correlated with differential methylation in SETD2 cases show an enrichment for processes such as neoplasm invasiveness, in particular kidney neoplasm, which suggests that SETD2 mutations may be involved in cancer aggressiveness through DNA methylation." (PMID 37528416, 2023). "Consistent with prior studies highlighting the potential role of chromatin dysregulation in aggressive renal neoplasms, we frequently identified mutations in chromatin remodeling genes, particularly BAP1 and SETD2, both of which have often been associated with rhabdoid features in ccRCC." (PMID 40940841, 2025). "Indeed, although combined deletion of Vhl and Pbrm1 results in multifocal clear cell kidney cancers indicating that Setd2 inactivation is not required for kidney tumor initiation, tumors did not metastasize in this model and loss of SETD2 may be an essential step in this process." (PMID 37418588, 2024).
lymphoma (7 papers, 2018 to 2025). A malignant (clonal) proliferation of B- lymphocytes or T- lymphocytes which involves the lymph nodes, bone marrow and/or extranodal sites. "Although guadecitabine is no longer being developed for myeloid disease, the recent registration of an orally available decitabine formulation provides an alternative and convenient backbone for future studies in biologically rational PTCL subgroups including tTFH and SETD2 mutated lymphoma." (PMID 35459873, 2022). "On a genetic level, these lymphomas show frequent gains of 8q24 (including MYC gene) and recurrent mutations of STAT5b, JAK3, GNAI2, and SETD2." (PMID 37345080, 2023). "The finding that inactivation of SETD2 sensitizes lymphoma cells to guadecitabine is consistent with our clinical observation, with the only patient on study carrying a SETD2 mutation responding to treatment." (PMID 35459873, 2022). "We also found CNA from our assay could also reveal some lymphoma critical genes, such as TNFRSF14 in 1p36.32, TNFAIP3 in 6q23.3, and SETD2 in 3p21.31." (PMID 38313801, 2024).
myelodysplastic syndrome (7 papers, 2016 to 2025). A clonal hematopoietic disorder characterized by dysplasia and ineffective hematopoiesis in one or more of the hematopoietic cell lines. "Paradoxically, Setd2 loss conferred resistance to IFNγ-induced HSPCs exhaustion, which may contribute to the maintenance of Setd2-deficient HSPCs in our myelodysplastic syndrome (MDS) model under the inflammatory milieu." (PMID 41198622, 2025). "EZH2 mutation and SETD2 deficiency correlates with poor survival in myelodysplastic syndrome (MDS)." (PMID 36671446, 2022). "SETD2-deficient HSPC can acquire the ability to overcome growth disadvantage during the latency period, eventually acquiring to the malignant hematopoietic features of myelodysplastic syndrome (MDS)." (PMID 37359376, 2023). "SETD2 expression was highest in patients with 11q23 aberrations featuring MLL-translocations, as compared to samples with normal karyotype AML or myelodysplastic syndrome." (PMID 29777171, 2018).
gastric cancer (6 papers, 2020 to 2025). A primary or metastatic malignant neoplasm involving the stomach. "Studies have shown that the migration, proliferation and invasion abilities of the gastric cancer (GC) cell lines HGC-27 and AGS decreased as the level of SETD2 expression increased." (PMID 37359376, 2023). "Hence, SETD2 as SETDB1 and SETDB2 genes, two other H3K36 methyltransferases, are altered in gastric cancer (GC)." (PMID 39591760, 2025).
T-cell lymphoma (6 papers, 2016 to 2023). "Coherently, SETD2 gene is recurrently inactivated in a variety of B and T cell lymphomas." (PMID 35083135, 2021). "Furthermore, we have shown these cell lines to bear several characteristics which are typical for this type of T-cell lymphoma including the rearranged chromosome i(7q) and specific mutations in HIST1H3B, KDM7A, SETD2 and STAT5B." (PMID 31143370, 2019).
bladder cancer (5 papers, 2015 to 2023). "Mutation, amplification, and/or deletion of SETD2 were observed in 10% of bladder cancer (n=127)." (PMID 25611383, 2015). "However, comparison of SETD2 expression across several cancers demonstrated lower SETD2 expression in multiple cancers, including bladder cancer (fold changes −2.3 and −3 in two studies)." (PMID 25611383, 2015).
chronic lymphocytic leukemia (5 papers, 2016 to 2025). "For example, Non-MLL rearranged AML and chronic lymphocytic leukemia exhibit similar incidence rates of SETD2 mutations (6 and 7%, respectively), and a lower incidence (3%) has been reported in chronic lymphocytic leukemia." (PMID 32849799, 2020). "Defects in SETD2 have been also detected in many lymphoid malignancies such as precursor B-cell lymphoblastic leukemia, early-T-precursor lymphoblastic leukemia, diffuse large B-cell lymphoma, chronic lymphoblastic leukemia, small lymphocytic lymphoma and even in mast cell leukemia." (PMID 39591760, 2025).
gastrointestinal stromal tumor (5 papers, 2016 to 2025). "Generally speaking, in gastrointestinal stromal tumors (GIST) functional consequences of SETD2 mutations were investigated in primary tissues and cell lines and SETD2 has been described as a novel GIST tumor suppressor gene associated with disease progression." (PMID 39591760, 2025).
multiple myeloma (5 papers, 2021 to 2025). "SETD2 is recurrently mutated in a number of tumor types including multiple myeloma, particularly in the relapsed and refractory setting." (PMID 35127532, 2021). "A small molecular inhibitor of SETD2 has demonstrated preclinical efficacy by suppressing proliferation both in myeloma cell lines and in vivo mouse xenografts." (PMID 35127532, 2021). "Moreover, the novel chromatin-regulatory mechanism of lncRNA by interacting with epigenetic modifiers including m6A demethylase ALKBH5 and H3K36me3 methyltransferase SETD2 in myeloma progression elucidated intricate mechanism of tumor pathogenesis." (PMID 38145297, 2024). "However, CRISPR pooled screens have found that myeloma cells are in fact dependent on SETD2 for survival." (PMID 35127532, 2021). "However, the role of SETD2 in myeloma progress remains elusive." (PMID 38145297, 2024).
overgrowth syndrome (5 papers, 2015 to 2023). A group of syndromes caused by genetic birth defects that may lead to the development of malignancies. "This was consistent with these diseases being distinct, although extensive overlap of clinical signs between SETD2-associated phenotypes and other overgrowth syndromes related to NSD1, EZH2 or DNMT3A in Sotos, Weaver and Tatton-Brown-Rahman syndromes, respectively, has been reported." (PMID 33916664, 2021). "Consistent with this idea, mutations in the DNA methyltransferase gene DNMT3A, SETD2 and EZH2 have also been shown to cause overgrowth syndromes." (PMID 27688808, 2016). "Regarding VUS with a possible pathogenic cause, it is worth mentioning that patient AUT195 has a variant in the SETD2 gene described in the literature regarding Luscan–Lumish syndrome (OMIM #616831), an overgrowth syndrome with which we have great clinical experience." (PMID 38003033, 2023).
autism (4 papers, 2015 to 2023). Persistent deficits in social interaction and communication and interaction as well as a markedly restricted repertoire of activity and interest as well as repetitive patterns of behavior. "The SETD2 gene is known as an autism susceptibility gene reported in autism and was the highest rated and most likely candidate gene in this case." (PMID 25574603, 2015).
brain tumors (4 papers, 2018 to 2024). "It is interesting to note that the most common mutation in brain tumors, Setd2 R1439, was mutated in 4/30 ENTs." (PMID 38232086, 2024). "Nineteen primary brain tumors (fifteen at the University of Pennsylvania and four at CHOP) with SETD2 mutations were identified on routine NGS studies." (PMID 30419952, 2018). "The most frequent alteration in brain tumors, Setd2 R1439, was also found in 2/9 heart tumors." (PMID 38232086, 2024). "The most frequently altered residue in the brain tumors was Setd2 p.1439R." (PMID 38232086, 2024). "Set2 homologs, including NSD1, NSD2, NSD3, and SETD2, are frequently mutated, translocated, or amplified in a variety of human cancers, and oncohistone mutations that dysregulate H3K36 methylation cause pediatric brain tumors." (PMID 35263330, 2022).
breast tumors (4 papers, 2014 to 2025). "One of the first hypotheses that have been proposed for SETD2-dependent development of breast tumors relies on telomerase regulation through human telomerase reverse transcriptase (hTERT)." (PMID 39591760, 2025).
chronic myeloid leukemia (4 papers, 2019 to 2025). "We found that SETD2 protein deficiency, mirrored by H3K36me3 deficiency, is a nearly universal event in advanced‐phase chronic myeloid leukemia (CML) patients." (PMID 40275711, 2025). "Another study reported that JIB-04 targeted imatinib-resistant chronic myeloid leukemia (CML) cells by enriching H3K36me3 on tumor suppressor gene SETD2 promoter and enhancing its transcription." (PMID 40664642, 2025). "However, the detailed mechanisms through which SETD2 confers chronic myeloid leukaemia progression and resistance to therapy targeting on BCR‐ABL remain unclear." (PMID 31054182, 2019).
developmental delay (4 papers, 2020 to 2025). "Germline pathogenic variants in two genes encoding the lysine-specific histone methyltransferase genes SETD1A and SETD2 are associated with neurodevelopmental disorders (NDDs) characterized by developmental delay and congenital anomalies." (PMID 37166351, 2023). "According to the review of SETD2 mutations, most patients show speech and language developmental delay, motor developmental delay, variable degree of intellectual disability and behavioral problems, which is completely in accord with the symptoms of SETD2 knockout mice." (PMID 37025455, 2023).
Fanconi anemia (4 papers, 2018 to 2024). Fanconi anemia (FA) is a hereditary DNA repair disorder characterized by progressive pancytopenia with bone marrow failure, variable congenital malformations and predisposition to develop hematological or solid tumors. "WES revealed that HMCLs displayed frequent mutations in Fanconi anemia genes (PALB2 [12%], FANCI [12%], FANCA [9%], FANCD2 [9%], BRCA2 [9%]) as well as in helicases (such as RECQL4, 15%, and BLM, 15%) and epigenetic modifiers (e.g., TET2, 15% and SETD2, 6%)." (PMID 30545397, 2018). "Our studies show that genes like ATM, ATRX, RAD51C, along with members of the Fanconi Anemia pathway (FANC-B, C, E, I, L, and M), and SETD2, the methyltransferase regulating H3K36me3, were all associated with the combination of H3K36me3, γH2AX and enhanced R-loops." (PMID 39178326, 2024).
hepatocellular carcinoma (4 papers, 2021 to 2024). A malignant tumor that arises from hepatocytes. "Furthermore, the underlying mechanism of SETD2 in the development and progression of hepatocellular carcinoma is largely unknown." (PMID 39668826, 2024). "SETD2 loss promotes the occurrence and development of hepatocellular carcinoma (HCC), and therefore, further studies on the role of SETD2 and cholesterol homeostasis in tumorigenesis are warranted." (PMID 37359376, 2023). "The pancancer RNA-seq data from TCGA database showed that the expression of SETD2 was upregulated in hepatocellular carcinoma, so SETD2 might play oncogene role in hepatocellular carcinoma." (PMID 39668826, 2024). "SETD2 and H3K36me3 are closely correlated with the development and progression of hepatocellular carcinoma, but there are different ideas about whether SETD2 expression and H3K36me3 promote or inhibit hepatocellular carcinoma progression 13-15." (PMID 39668826, 2024). "Previous studies have shown that SETD2 and H3K36me3 are closely correlated with the development and progression of hepatocellular carcinoma, but there are different ideas about whether SETD2 expression and H3K36me3 promote or inhibit hepatocellular carcinoma progression 13-15." (PMID 39668826, 2024). "In hepatocellular carcinoma (HCC), RNA-Seq analysis of liver tissues from control and SETD2 KO mice showed that only a fraction of genes changed expression levels upon H3K36me3 reduction." (PMID 34715919, 2021). "The results from SETD2 silencing and SETD2 overexpression experiments demonstrated that SETD2 could promote the proliferation and migration of HCC cell lines; that is, SETD2 has an important role in promoting hepatocellular carcinoma." (PMID 39668826, 2024).
Huntington disease (4 papers, 2015 to 2023). Huntington disease (HD) is a rare neurodegenerative disorder of the central nervous system characterized by unwanted choreatic movements, behavioral and psychiatric disturbances and dementia. "The SETD2 encodes a Huntingtin-interacting protein B related to Huntington disease and known expression in the brain." (PMID 25574603, 2015). "Here, we report that SETD2 deficiency was found to be associated with decreased turnover of mutant-HTT protein and increased cellular toxicity, offering a novel link to Huntington disease." (PMID 36371383, 2022).
Macrocephaly (4 papers, 2022 to 2025). Occipitofrontal (head) circumference greater than 97th centile compared to appropriate, age matched, sex-matched normal standards. "Excluding the patients with missense mutations in the 1740th codon of SETD2, the rates of high stature (5/16) and macrocephaly (11/16) were higher." (PMID 37025455, 2023).